FAM25C (family with sequence similarity 25 member C)
Synonyms: bA164N7.4
Tractability: No criterion of Open Targets' tractability assessment is met for any kind of drug.
Gene: Protein-coding gene on chromosome 10 (47,995,322 to 47,999,791, reverse strand). Ensembl gene ENSG00000276430.
Genetic constraint (gnomAD): Loss-of-function variants: 3 observed, 4.65 expected, observed/expected ratio (o/e) 0.64, 90% interval 0.29 to 1.57. That is too few expected variants to judge how well the gene tolerates losing a copy. Missense variants: 31 observed, 58.86 expected, observed/expected ratio (o/e) 0.53, 90% interval 0.4 to 0.71. Synonymous variants: 18 observed, 24.31 expected, observed/expected ratio (o/e) 0.74, 90% interval 0.51 to 1.1.
Homologues: Orthologues: mouse Fam25a (80% identical), rat Fam25a (80% identical), guinea pig Fam25a (78% identical), dog FAM25A (71% identical). Paralogues in human: FAM25A (100% identical), FAM25G (100% identical).
Diseases named in the same sentence as FAM25C in open-access papers:
FAM25C is named in the same sentence as 3 diseases in open-access papers, as found by Europe PMC text mining. Sharing a sentence is not in itself a finding about the gene and the disease. The quoted sentences say what the papers report.
diabetes (1 paper, 2024). "Loci for the other genes—PTP4A1, APOBR, BMS1P4-AGAP5, MAPK8IP1P1, GYS2, FAM25C, and GK5–were formerly associated with traits involved with comorbidities of OSA, i.e., BMI, weight, triglycerides, blood pressure, stroke, brain volume, cortical thickness, mood, insulin, and diabetes." (PMID 39457448, 2024).
FAM25C also shares sentences with these, for which no sentence is quoted: Esotropia (1 paper); Stroke (1).